VEGFA (vascular endothelial growth factor A)
Diseases named in the same sentence as VEGFA in open-access papers (continued):
Sharing a sentence is not in itself a finding about the gene and the disease.
tumor (continued). "Additionally, interface-derived and tumor-derived mast cells had high expression levels of VEGFA and VEGFB genes, suggesting potential functions of promoting angiogenesis." (PMID 37644609, 2023). "The upregulaion of BIRC5 expression recognized and enhanced by IGF2BP3 could then promote the tumour’s progression, metastasis, and VEGFA-regulated angiogenesis." (PMID 37284313, 2023). "The XBP1/PDIA4/VEGFA regulatory axis may be responsible for how GBM cells obtain nutrients within the poor tumor microenvironment by accelerating angiogenesis." (PMID 36997943, 2023). "Analysis of the SEP21 sample showed low PD-1/PDL-1 and high VEGFA levels at the tumor locations." (PMID 37704757, 2023). "Indeed, the upregulation of 37 different MYC-regulated genes including BCL2, CCND1, PCNA, PGK1, and VEGFA, all promote tumor formation." (PMID 36831657, 2023). "Expression of VEGFA (p = 0.0110) was higher in high stromal STAT3 tumours." (PMID 37199043, 2023). "For example, bevacizumab inhibits tumor angiogenesis by inhibiting the binding of VEGFA to VEGFR2." (PMID 38201620, 2023). "VEGFA is a major factor driving the expansion of tumor vascular beds." (PMID 37980532, 2023). "Moreover, knockdown of circASH2L repressed tumor xenograft angiogenesis and lymphangiogenesis through suppression of VEGFA." (PMID 37234708, 2023). "Moreover, VEGFA is considered a key modulator of angiogenesis and is generally highly expressed in cancer and correlated with tumor progression, angiogenesis, and TNBC invasion." (PMID 38049525, 2023). "Additionally, others have shown that VEGFA-mediated development of CRC tumor angiogenesis was impeded by inhibition of MMP7." (PMID 36672201, 2023). "Referring to the combination of gene copy number variation of VEGFA and its overexpression in the tumor, it was noteworthy that in the Control Disease group, the two variables are combined in 37.5% of cases compared with 7.14% observed in the Rapid Progression group." (PMID 37893095, 2023). "In addition, VEGFA direct and indirect targets were highly represented among the DEGs between tumor and blood in the myeloid cell types." (PMID 37487666, 2023). "Most anti-angiogenic approaches focus on inhibiting the signaling pathway of pro-angiogenic factors, either by interacting with the factor itself (e.g., BVZ, the anti-VEGFA) or by blocking its receptor on the tumor cell surface (e.g., sunitinib, the anti-VEGFR)." (PMID 37508458, 2023). "Notably, IPA Upstream Regulator Analysis identified VEGFA, a central player in tumor growth and vascularization across multiple tumor types, as a key upstream inducer of genes in the TME (false discovery rate p=5.65×10−13)." (PMID 37487666, 2023). "Among all the growth factors detected in GBM, VEGFA was highly expressed in MDMs and tumor cells, suggesting that increased MDMs could lead to upregulation of VEGFA and promote tumor growth." (PMID 36761752, 2023). "Our findings showed the associations between the high expression of VEGFA, VEGFC, and PGF and poor prognosis across various cancers, suggesting that they may serve as risk factors for tumor progression." (PMID 37852616, 2023). "Since VEGFA has been reported to be associated with increased cellular invasiveness, we hypothesized that miRNA-383-5p regulates tumor invasiveness through VEGFA." (PMID 37592783, 2023). "Inhibiting VEGFA activity can inhibit the tumour growth and tumour angiogenesis of GC." (PMID 37794689, 2023). "Furthermore, they suppressed the expression of matrix metalloproteinases and vascular endothelial growth factor-A (VEGFA), molecules that are related to angiogenesis and tumor invasion." (PMID 37237914, 2023). "CAFs produce angiogenesis regulators, such as VEGFA, PDGFC, FGF2, CXCL12, osteopontin, and CSF3 to promote the growth of tumor-associated blood vessels by recruiting myeloid cells and accelerate tumor angiogenesis by attracting vascular endothelial cells and recruiting monocytes." (PMID 37784082, 2023).
tumor (continued). "The increase in VEGFA expression of tumor cells treated with anti-PD-L1 antibodies may only partially explain the tumor cell side of the resistance mechanism." (PMID 38152616, 2023). "In the independent validation set, we found regulatory chains with GAS6, TIMP1, SPP1, and VEGFA as ligands, which was consistent with our findings above, indicating that these regulatory relations may be ubiquitous in tumor cells and macrophages." (PMID 37189418, 2023). "Next, we investigated whether Erk1/2/HIF-1α/STAT3/VEGFA is critical for tumor angiogenesis under DOKD feeding." (PMID 37239383, 2023). "Moreover, VEGFA was significantly higher in tumour tissue than in normal tissue suggesting that it played an important role in HCC." (PMID 36729917, 2023). "Chronic VEGFA signaling promotes glycolysis in endothelial cells and feeds into this positive feedback loop: tumor growth generates a hypoxia-induced acidic and nutrient-starved tumor microenvironment, which then promotes further tumor growth through angiogenesis and immunosuppression." (PMID 36765912, 2023). "Injection of VEGFA-165 partially restored the tumor growth inhibition induced by USP22 knockdown." (PMID 36906615, 2023). "In addition, p19ARF suppresses vascular endothelial growth factor A (VEGFA) expression through repression of the translation of VEGFA mRNA, thereby suppressing tumor angiogenesis." (PMID 38132337, 2023). "Increased VEGFA mRNA (Vegfa) production has been reported in Htatip2-silenced tumor cells." (PMID 37847559, 2023). "In PitNETs, IL6 may contribute to hormone release, to tumor growth and proliferation, and to the production of angiogenic factors, such as vascular endothelial growth factor-A (VEGF-A)." (PMID 37958474, 2023). "VEGFA is pivotal in controlling angiogenesis, and the hypoxic status in tumor tissues could upregulate the secretion of the pro-angiogenic factor VEGFA." (PMID 37854285, 2023). "EPCs may be recruited from bone marrow mobilized by vascular endothelial growth factor A (VEGFA) or C-X-C motif chemokine 12 (CXCL12) released by tumor-infiltrating myeloid cells or cancer cells." (PMID 38148844, 2023). "Among them, 51 tumour tissues and three peritumoral tissues showed high expression of VEGFA." (PMID 36729917, 2023). "In resistant cells, the overall effect of the PTX-Elacridar combined treatment was inhibitory of tumor growth, nevertheless these combined drugs determined a nuclear accumulation of TUBβIII, as well as the induction of pro-angiogenic genes (VEGFA, VEGFC, Ang2)." (PMID 36874116, 2023). "In addition, the expression of USP22 was also positively correlated with that of VEGFA in xenograft tumor." (PMID 36906615, 2023). "IHC analysis of xenograft tumors indicated stronger staining of VEGFA and CD31 in LV-PDIA4 xenograft tumors, which indicated tumor-derived PDIA4 could promote VEGFA secretion and angiogenesis in vivo, as we had speculated." (PMID 36997943, 2023). "Neutrophils are the primary source of VEGFA expression in the tumor microenvironment of NSCLC." (PMID 38155968, 2023). "Our findings suggest that GSTZ1 may serve as an important tumor suppressor owing to its ability to inhibit the HIF-1α/VEGFA axis in HCC." (PMID 37906252, 2023). "ALK regulated VEGFA production and tumor angiogenesis in NSCLC, dependent on both HIF1α and HIF2α." (PMID 36012123, 2022). "Additionally, some study showed that platelet also promote tumor metastasis and angiogenesis by releasing various growth factors such as vascular endothelial growth factor-A." (PMID 36326905, 2022). "Moreover, in 90 CRC tissue samples, we found that the expression of VEGFA was significantly higher in tumor than that in paired normal tissues." (PMID 35053547, 2022). "Other immune evasion mechanisms included the upregulation of immune checkpoints such as programmed cell death-1 (PD-1) and the overexpression of vascular endothelial growth factor A (VEGF-A) an inducer of tumour angiogenesis, commonly seen in BRCA1/2-mutant HGSOC." (PMID 36159999, 2022).
tumor (continued). "Considering β-catenin could transcriptionally activated VEGFA and MMPs to regulate tumor angiogenesis and metastasis, we wondered whether β-catenin is implicated in MIIP-elicited tumor-suppressing effect in TNBC." (PMID 36130933, 2022). "VEGFA functions in the modulation of cancer immune response, which could result in escape of tumour cells from the surveillance of the immune system." (PMID 35844558, 2022). "In NPC, Hotair could promote tumor development by directly activating the transcription of angiogenic factor VEGFA and upregulating the expression of VEGFA and Ang2 mediated by GRP78 or through FASN." (PMID 35602292, 2022). "Tumour specimens from 188 patients were analysed by gene expression profiling, targeted exome sequencing, immunohistochemistry and fluorescence in situ hybridisation for VEGFA." (PMID 36300092, 2022). "CAFs secrete VEGFA in the tumor microenvironment to induce angiogenesis and promote tumor growth." (PMID 35626012, 2022). "VEGFA secretion maintains endothelial cell viability in the tumour surroundings." (PMID 35106125, 2022). "Furthermore, VEGFA-dependent angiogenesis and ephrin-Eph bidirectional signaling pathways were also found in Endo_1 and tumor cells." (PMID 35999201, 2022). "Multiple signaling pathways, including the angiogenesis, hypoxia, and VEGF pathways were significantly enriched, which encouraged us to further explore the underlying mechanism by which swimming attenuates tumor angiogenesis and the HIF-1α/VEGFA pathway activation." (PMID 35291563, 2022). "Among these miRNAs, miR-106a-5p has been proved to be a tumor suppressor by targeting VEGFA in RCC." (PMID 36090028, 2022). "Furthermore, TNF-α, VEGFA, and c-Myc were considered to serve important roles in tumorigenesis and tumor development, which can be regulated by HDAC1." (PMID 35053925, 2022). "In Kaposi sarcoma, it has been shown that activation of the K-Ras-B-Raf-ERK pathway results in downregulation of ACKR2 expression, unleashing CCR2-mediated recruitment and activation of M2-like phenotype of macrophages, which support angiogenesis and tumor growth via producing VEGFA." (PMID 35677043, 2022). "Furthermore, quantitative analysis of the RNA levels indicated a reduction of VEGFA (the isoform mainly involved in tumour angiogenesis; Claesson‐Welsh & Welsh, 2013) in ERO1 KO cells under hypoxic conditions, but not that of VEGFB." (PMID 35853086, 2022). "Intriguingly, together with CD274 (PD-L1), CD276 (B7-H3) and VEGFA were both highly expressed in the cold tumours, which could be further investigated as novel immunotherapy targets for such patients." (PMID 36267973, 2022). "Additionally, enriched signaling pathways other than HIF-1α/VEGFA should be investigated in tumor tissues after swimming." (PMID 35291563, 2022). "Finally, VEGFA expression in OC cells has been considered a poor prognostic factor as it exerts an influence on tumor immune evasion via the recruitment and activation of myeloid-derived suppressor cells." (PMID 36230822, 2022). "Therefore, to study the angiogenesis effects of Bev and Lis, we investigated the levels of VEGFA in the xenograft tumor tissues of mice in the different treatment groups at different time points." (PMID 35847929, 2022). "VEGFA produced under hypoxic conditions will recruit pro-angiogenic neutrophils that may participate in tumor angiogenesis and further immune response." (PMID 35216427, 2022). "For instance, an increased level of infiltrated tumor-associated macrophages is found around tumors, promoting tumor progression by enhancing vascular endothelial growth factor A-mediated angiogenesis and suppressing cytotoxic T cell-regulated anti-tumor response." (PMID 35978826, 2022). "Molecular and cellular mechanisms underlying tumor resistance to VEGFA neutralization are diverse and not fully understood." (PMID 36077762, 2022).
tumor (continued). "In several murine and human cancer models, it has been demonstrated that VEGFA stimulates the tumor-initiating epithelial–mesenchymal transition and metastasis, and that VEGFA expression levels are positively correlated with BRAC purity and neutrophil infiltration levels." (PMID 35845599, 2022). "As a transcription factor, β-catenin could activate the transcription of several tumor-promoting molecules, including VEGFA, MMPs and EMT-related proteins, which contribute to enhanced tumor metastasis capacity." (PMID 36130933, 2022). "VEGFA-expressing cDCs are known to promote angiogenesis in inflamed lymph nodes, but these interactions with angiogenic ECs were unknown in the tumor context." (PMID 36127427, 2022). "As expected, swimming obviously reduced both the mRNA and protein expression of VEGFA and protein expression of VEGFR2, which might be one of the underlying mechanisms by which swimming suppresses tumor angiogenesis." (PMID 35291563, 2022). "To support our hypothesis, we also investigated the transcriptional activity of STAG1 and the tumor angiogenesis promoting factor, VEGFA." (PMID 36052535, 2022). "As a part of the growth factor family, VEGFA has a strong ability to promote the angiogenic environment, such as by increasing microvascular density and vascular permeability, finally, leading to tumor resistance to angiogenic therapy." (PMID 36238299, 2022). "Thus, we reached the conclusion that the overexpression of the LBH gene is associated with attenuated angiogenesis, EMT progression and VEGFA expression in NPC tumor xenografts." (PMID 34975330, 2022). "Furthermore, ZFAS1 was found to promote the progression of CRC by competitively binding miR-150-5p, which plays a tumor suppressor role in CRC by targeting VEGFA." (PMID 36545127, 2022). "Taken together, this study reported a new regulatory axis linc00958/miR-185-5p/RSF-1 in cisplatin resistance and tube formation in CC via AKT1/GSK3β/VEGFA pathway and knockdown of linc00958 could also inhibit the tumor growth and angiogenesis." (PMID 36056431, 2022). "Thereby, it seems that VEGFA inhibition may entice T cell activation at higher levels, facilitating T cell-mediated anti-tumor immunity." (PMID 35392964, 2022). "Furthermore, by performing tumor metastasis PCR array and luciferase reporter assay, we find that the expression of VEGFA is regulated by miR-29c through direct targeting of its 3'-UTR." (PMID 36484007, 2022). "Tumor angiogenesis is mainly dependent on VEGFA-driven responses." (PMID 39296516, 2022). "Vascular endothelial growth factor A (VEGFA) plays a role in tumor growth and metastasis." (PMID 35771149, 2022). "Then, it was confirmed that miR-210 could regulate EFNA3 expression; further mechanistic analysis revealed that miR-210 could promote tumor progression via the PI3K/AKT/VEGFA or Wnt/Β-catenin/RHOA pathways." (PMID 36466111, 2022). "In order to do this, different mechanisms have been proposed: tumour growth can be caused through eosinophil-derived CCL22, by thymic stromal lymphopoietin (TSLP) that induces angiogenesis via VEGFA and by eosinophils-derived epidermal growth factor (EGF) along with TGF-β." (PMID 35406451, 2022). "Furthermore, Ang2 is expressed prior to VEGFA in growing tumor vessels and enhances angiogenesis in the presence of VEGFA." (PMID 35805939, 2022). "Angiogenesis assay uncovered that combined processing with Rg3 and 5-FU could restrain tumor angiogenesis by markedly reducing the expression of VEGFA." (PMID 35799655, 2022). "Tumors with a high cell proliferation rate and undergoing active growth have a significantly reduced oxygen supply, especially cells in the core of the tumor, and activation of HIF-1 promotes the release of more pro-angiogenic factors, especially VEGFA, from tumor cells and stromal cells." (PMID 36483051, 2022).
tumor (continued). "Thus, the hypoxic environment in a growing tumor or in the developing retina is seen as a source of the principle angiogenesis driver vascular endothelial growth factor A (VEGF-A)." (PMID 35701563, 2022). "VEGFA signaling played a crucial role in the progression of angiogenesis-related diseases, particularly in cancers; agents blocking VEGFA have been reported that could effectively inhibit tumor growth and metastatic spread." (PMID 36147313, 2022). "In addition, the binding of circSMARCA5 to SRSF1 also regulated the mRNA splicing of VEGFA, thereby preventing tumor angiogenesis, and suppressing the development of glioblastoma." (PMID 36231036, 2022). "Moreover, they were also enriched in pathways such as VEGFA-VEGFR2 signaling pathway and urea cycle and associated pathways, which were relevant to tumor development and angiogenesis." (PMID 35607442, 2022). "Several genes were recognised targets of those microRNAs, and at least two (LOX, VEGFA) were already known to be involved in GBM tumourigenesis: LOX, a cofactor of HIF-1 which helps tumour cell to adapt to hypoxia, and VEGFA, known to be upregulated in older GBMs." (PMID 35327445, 2022). "If the translation of VEGFA could be affected, tumor growth and metastasis could be inhibited to some extent." (PMID 35054929, 2022). "Interestingly, the significant increase in VEGFA mRNA expression in post-hysterectomy compared to pre-hysterectomy biopsies in benign endometrium was lost when only pipelle samples were considered." (PMID 35775066, 2022). "Accumulating evidence has shown that VEGFA plays a key role in tumour angiogenesis and VM." (PMID 35669101, 2022). "In addition, clinical data indicate that VEGFA and tumor-derived VEGFD induce prometastatic lymphangiogenesis and are associated with increased lymph node metastasis." (PMID 36497411, 2022). "Specifically, in the tumor microenvironment, the reduced VEGFA protein levels in LBH-overexpressing NPC tissues might be due to the comprehensive effects of both NPC cells and HUVECs." (PMID 34975330, 2022). "Moreover, consistent with the in vitro results, decreased expression of SP1 and VEGFA protein was observed in both nude mice tumor tissues fixed with paraformaldehyde and fresh tumor tissues." (PMID 36467048, 2022). "VEGFA is a well-known regulator of human tumor angiogenesis and metastasis." (PMID 35651811, 2022). "CAF-derived PDGFC, together with VEGFA, mediates tumor growth, metastasis, and angiogenesis." (PMID 35327514, 2022). "SRC-1 promotes tumor angiogenesis by raising HIF1α-mediated VEGFA expression." (PMID 34696659, 2022). "CXCL8/11/14 and VEGFA promote tumor angiogenesis in different ways." (PMID 36246978, 2022). "In a tumor xenograft model, TAMs enhance VEGFA-driven tumor angiogenesis." (PMID 35672862, 2022). "In addition to human tumor cells, connexin was found to negatively regulate VEGFA in animal tumor cells." (PMID 35783340, 2022). "Cetuximab (anti-EGFR monoclonal antibody) and bevacizumab (anti-VEGFA monoclonal antibody) enhanced the distribution of the virus in the entire tumor by inhibiting angiogenesis, expanded the number of apoptotic cells, and successfully induced a synergistic anti-tumor effect." (PMID 35371972, 2022). "In this study, we found a novel mechanism that PELP1 regulates tumor angiogenesis by promoting the expression of VEGFA, and may become a new target for anti-tumor angiogenesis therapy." (PMID 35053547, 2022). "Collectively, these results suggest that the CXC chemokine-VEGFA network may influence the development of COAD by increasing tumor angiogenesis." (PMID 36246978, 2022). "Increase in VEGFA levels mediated by STAT3-signaling plays a critical role in tumor angiogenesis." (PMID 36010595, 2022). "VEGFA is a secreted protein and a key regulator of tumor blood vessel formation." (PMID 35785190, 2022). "VEGFA is well known for its role in promoting tumor angiogenesis." (PMID 35935576, 2022).